PSKH1 (protein serine kinase H1)
Description:
Serine/threonine protein kinase that may be involved in the regulation of pre-mRNA processing. It may phosphorylate components of nuclear splice factor compartments (SFC), such as non-snRNP splicing factors containing a serine/arginine-rich domain (SR proteins). Reversible phosphorylation of SR proteins may cause their release into the nucleoplasm and change their local concentration, thereby influencing alternative splicing.
Synonyms: PFIC13
Tractability: Small molecule: a high-quality ligand is known; it belongs to a druggable protein family. Antibody: UniProt places it where antibodies can reach, with high confidence; its Gene Ontology location is reachable by antibodies, with high confidence; the Human Protein Atlas places it where antibodies can reach. PROTAC: ubiquitination databases record sites on it; a small molecule that binds it is known.
Target class: Enzyme; Transferase
Gene: Protein-coding gene on chromosome 16 (67,893,254 to 67,929,676, forward strand). Ensembl gene ENSG00000159792.
Subcellular location: Golgi apparatus; Cytoplasm, cytoskeleton, microtubule organizing center, centrosome; Nucleus speckle; Endoplasmic reticulum membrane; Cell membrane; Cytoplasm
Subcellular location (Human Protein Atlas): Nuclear speckles; Cytosol; Plasma membrane; Primary cilium
Gene Ontology:
Molecular function: protein binding; protein serine kinase activity; protein serine/threonine kinase activity; ATP binding; protein kinase activity
Cellular component: cytoplasm; cytosol; endoplasmic reticulum membrane; Golgi apparatus; nuclear speck; plasma membrane; centrosome
Genetic constraint (gnomAD): Loss-of-function variants: 12 observed, 27.39 expected, observed/expected ratio (o/e) 0.44, 90% interval 0.28 to 0.71. The upper end of that interval is the gene's LOEUF score, 0.71, which puts it in group 2 of 6, group 1 being the genes least tolerant of losing a copy. Missense variants: 431 observed, 620.15 expected, observed/expected ratio (o/e) 0.69, 90% interval 0.64 to 0.75. Synonymous variants: 213 observed, 245.69 expected, observed/expected ratio (o/e) 0.87, 90% interval 0.77 to 0.97.
Homologues: Orthologues: chimpanzee PSKH1 (100% identical), macaque PSKH1 (99% identical), rabbit PSKH1 (99% identical), pig PSKH1 (98% identical), rat Pskh1 (98% identical), mouse Pskh1 (98% identical), guinea pig PSKH1 (97% identical), dog PSKH1 (96% identical), tropical clawed frog pskh1 (82% identical), zebrafish pskh1 (81% identical). Paralogues in human: PSKH2 (57% identical), CAMK1D (35% identical), CAMK1 (33% identical), PNCK (33% identical), CAMK1G (32% identical), DCLK1 (31% identical), DCLK2 (31% identical), CAMKV (30% identical), CAMK2D (29% identical), CAMK2G (28% identical), CAMK2B (28% identical), CAMK2A (28% identical), and 10 more.
Diseases named in the same sentence as PSKH1 in open-access papers:
PSKH1 is named in the same sentence as 10 diseases in open-access papers, as found by Europe PMC text mining. Sharing a sentence is not in itself a finding about the gene and the disease. The quoted sentences say what the papers report.
colon cancer (3 papers, 2019 to 2023). "Meanwhile, miR-566 mediates cell migration and invasion in colon cancer cells by direct targeting of PSKH1." (PMID 34305636, 2021). "Cancer metastasis plays roles in the advance of cancer, and in this study, we first confirmed that miR-566 is involved in colon cancer metastasis through targeting PSKH1." (PMID 31866763, 2019). "Elevated PSKH1 expression was involved in regulating migration and invasion of colon cancer cells." (PMID 37751451, 2023).
breast carcinoma (1 paper, 2020). "In breast cancer (BRCA), overexpression of six dark kinases is associated with decreased overall survival (ALPK3, CSNK1A1L, CSNK2A3, NRK, POMK, and PSKH1)." (PMID 33205077, 2020).
coronary heart disease (1 paper, 2025). "Only recently was the loss of kinase activity causatively linked to kidney ciliopathies in human patients, supporting an earlier attribution of PSKH1’s involvement in heart cilia organization in mice from a mutagenesis screen for coronary heart disease regulators." (PMID 39964718, 2025).
kidney cancer (1 paper, 2025). Primary or metastatic malignant neoplasm involving the kidney. "Protein Serine Kinase H1 (PSKH1) was recently identified as a crucial factor in kidney development and is overexpressed in prostate, lung, and kidney cancers." (PMID 39964718, 2025).
prostate carcinoma (1 paper, 2012). A carcinoma that arises from epithelial cells of the prostate gland. "This study demonstrates the applicability of lentiviral-based shRNA for conducting phenotypic screens and identifies MAP3K11, DGKD, ICK, CIT, GALK2, and PSKH1 as regulators of prostate cancer cell growth." (PMID 22761715, 2012). "It is plausible that the requirement for CIT, GALK2, and PSKH1 varies depending upon the tumorigenic state since the mRNA levels of these kinases increase as prostate cancer progresses." (PMID 22761715, 2012). "This study further demonstrates the applicability of lentiviral based shRNA for conducting phenotypic screens to identify targets involved in a variety of biological processes, and establishes MAP3K11, DGKD, ICK, CIT, GALK2, and PSKH1 as regulators of prostate cancer cell growth." (PMID 22761715, 2012).
cancer (2 papers, 2019 to 2025). A tumor composed of atypical neoplastic, often pleomorphic cells that invade other tissues. "In addition, we found that PSKH1 is a target of miR-566, and reintroduction of PSKH1 expression reversed the effects of miR-566 on cancer cell growth and metastasis." (PMID 31866763, 2019). "Interest in the biological functions of one such CAMK member, Protein Serine Kinase H1 (PSKH1), has recently grown owing to its implication as a crucial factor in kidney development and the association of PSKH1 overexpression with several cancers, including those of the prostate, lung, and kidney." (PMID 39964718, 2025).
PSKH1 also shares sentences with these, for which no sentence is quoted: atherosclerosis (1 paper); erythroleukemia (1); respiratory diseases (1); tumor (1).